PRKAA1 (protein kinase AMP-activated catalytic subunit alpha 1)
Diseases named in the same sentence as PRKAA1 in open-access papers (continued):
Sharing a sentence is not in itself a finding about the gene and the disease.
atherosclerosis (16 papers, 2017 to 2026). A disease characterized by the build-up of fatty material and calcium deposition in the arterial wall resulting in partial or complete occlusion of the arterial lumen. "We also examined whether Prkaa1 deficiency-mediated decreased leukocyte recruitment reduces diet-induced atherosclerosis." (PMID 33511118, 2020). "Functional deficits in Prkaa1-deficient ECs could be rescued by a gene therapy that increased EC glycolysis and prevented mice from accelerated atherosclerosis." (PMID 30405100, 2018). "Rescue of the impaired glycolysis in Prkaa1-deficient endothelial cells through Slc2a1 overexpression enhances endothelial cell viability and integrity of the endothelial cell barrier, and reverses susceptibility to atherosclerosis." (PMID 30405100, 2018). "Collectively, we have shown using PRKAA1-KD in human cells and Prkaa1-deficient mice that EC glycolysis plays a vital role in EC proliferation, maintenance of the EC monolayer, and the development of atherosclerosis." (PMID 30405100, 2018). "Here, we examined glycolysis in Prkaa1-deficient myeloid cells and the effects of this changed metabolism to myeloid cell recruitment and survival, as well as to the development of chronic inflammatory diseases, including diet-induced diabetes and atherosclerosis." (PMID 33511118, 2020). "This paradoxical nature extends to OS, which increases PRKAA1/AMPKα1 to induce glycolysis; yet its absence in ECs exacerbates atherosclerosis." (PMID 40890841, 2025). "Our previous study showed that Prkaa2 knock out (AMPKα2−/−) are more prone to atherosclerosis (AS) than Prkaa1 knock out (AMPKα1−/−) mice model." (PMID 36513627, 2022). "In contrast, Apoe–/– mice with Prkaa1 deletion or myeloid Prkaa1 deletion showed reduced monocyte differentiation and survival, thus attenuating the initiation and progression of atherosclerosis." (PMID 33511118, 2020). "PRKAA1-mediated endothelial metabolic homeostasis protects against the development of atherosclerosis." (PMID 30405100, 2018). "Here the authors unveil a protective role for glycolysis by showing that endothelial deletion of Prkaa1 accelerates atherosclerosis in hyperlipidemic mice through a reduction of glycolytic metabolism." (PMID 30405100, 2018). "To assess the functional role of endothelial Prkaa1 in atherosclerosis, we first examined the levels of Prkaa1 and its phosphorylated form (pPrkaT172) in the arterial endothelium of C57BL/6j mice, a strain of mice susceptible to diet-induced atherosclerosis." (PMID 30405100, 2018). "PRKAA1/AMPKα1-mediated glycolysis is vital to support increased proliferation of ECs and thus helps to preserve EC barrier integrity in vulnerable atheroprone regions and to protect mice from the development and progression of atherosclerosis." (PMID 30405100, 2018). "The effect of Prkaa1 deletion on plasma cholesterol levels, circulating monocytes and others may be important in atherosclerosis, although the Slc2a1 rescue experiment has assessed the effects of PRKAA1-driven glycolysis." (PMID 30405100, 2018). "Endothelial HIF1A and PRKAA1 play complex roles in atherosclerosis." (PMID 30405100, 2018). "Thus, this study highlights an important role of the PRKAA1–glycolysis–endothelial proliferation axis in protecting mice against atherosclerosis." (PMID 30405100, 2018). "Thus, mice with myeloid deletion of Prkaa1 exhibit less severe and more stable atherosclerosis." (PMID 33511118, 2020). "(iii) PRKAA1 and HIF1A have pleiotropic effects unrelated to glycolysis that also influence atherosclerosis." (PMID 30405100, 2018). "Our results indicate that AMPKα1/PRKAA1-regulated metabolism supports monocyte recruitment and macrophage viability, contributing to the development of diet-induced metabolic disorders including diabetes and atherosclerosis." (PMID 33511118, 2020).
atherosclerosis (continued). "Therefore, PRKAA1 KD ECs might have a decreased level of FAO, and decreased FAO may also be one of the factors reducing endothelial proliferation and accelerating atherosclerosis." (PMID 30405100, 2018).
Insulin resistance (14 papers, 2011 to 2025). Increased resistance towards insulin, that is, diminished effectiveness of insulin in reducing blood glucose levels. "The LS diet increased the expression of genes related to insulin resistance (ApocIII, G6pc, Pck1) and reduced those involved in oxidative capacity (Prkaa1, Prkaa2, Ppara, Lipe) and lipoprotein assembly (Mttp)." (PMID 34202724, 2021).
melanoma (14 papers, 2014 to 2025). A malignant, usually aggressive tumor composed of atypical, neoplastic melanocytes. "While we did not detect Prkaa2 expression in splenic and lymph node Treg cells of mice bearing subcutaneous B16 melanoma tumor grafts, we found that control Treg cells upregulated the expression of Prkaa1 and Prkaa2 in the TME." (PMID 40100289, 2025). "Further analysis also revealed that Pdcd1 was negatively correlated with AMPK subunit mRNAs including Prkaa1, Prkaa2, and Prkag1 in TCGA database obtained from prostate, melanoma, and breast cancer patients." (PMID 34649584, 2021). "We tested this hypothesis by performing genome-wide DNA methylation profiling of Prkaa1/2fl/flFoxp3YFP–Cre and control Treg cells sorted from B16 melanoma tumors and from spleens at homeostasis." (PMID 40100289, 2025). "Interestingly, the top two upregulated genes in melanomas from RHC were PRKAA1 (fold change=1.37, p=0.08) and PIK3C3 (fold change=1.23, p=0.09) while the top two downregulated were YWHAG (fold change=0.62, p=0.29) and CLN3 (fold change=0.77, p=0.3)." (PMID 28030792, 2017). "This is in marked contrast with the results for the PRKAA1 gene encoding AMPK-α1, where just seven mis-sense mutations in total were reported in the cBioPortal database in skin cancer and melanoma in, with up to five of those having no apparent effect." (PMID 37962491, 2023). "In single-cell RNA-seq dataset which was originated from melanoma tissue (GSE72056), we downloaded the TPM dataset file and sorted any values more than 3 TPM for cells that highly expressed Foxp3 transcripts and excluded invalid TPM values for Pdcd1 and Prkaa1 expression." (PMID 34649584, 2021).
diabetes (13 papers, 2014 to 2025). "Dysregulated PRKAA1 expression is linked to several ER stress-related diseases, including metabolic disorders (e.g., diabetes, cardiovascular diseases) and tumor invasiveness." (PMID 39850756, 2024). "Meanwhile, the protein kinase AMP-activated catalytic subunit alpha 1(PRKAA1) has been identified as involved in multiple diseases, including leukemia, heart ischemia/ reperfusion injury in Diabetes, wound healing, and osteoarthritis via autophagy 37, 43-45." (PMID 37705752, 2023). "Furthermore, two diabetes related drugs, Phenformin and Metformin, target the two subunits of AMPK, PRKAA1 and PRKAB1." (PMID 25399255, 2014).
Hepatic steatosis (12 papers, 2017 to 2026). Steatosis is a term used to denote lipid accumulation within hepatocytes. "In hepatocytes, PRKAA1 drives fatty acid oxidation and decreases lipogenesis, protecting against fatty liver disease." (PMID 35637448, 2022). "Overexpression of AMPK-α1 in the liver ameliorated hepatic steatosis in hyperlipidemic T2D rats, while Prkaa1-specific deletion in the mAMPKα1-KO mice muscle resulted in T2D characteristics including hyperglycemia, hyperlipidemia, and increased muscle TG contents when they were fed a high-fat diet." (PMID 35055468, 2022). "PRKAA1 and LIPE in Ethiopian humans and PPARA in Tibetan humans are both associated with lipid metabolism, which can be negatively impacted by chronic hypoxia as it increases the risk of developing fatty liver disease." (PMID 31154977, 2019).
lung carcinoma (12 papers, 2016 to 2025). "Like CC, silencing PRKAA1 sensitized lung cancer cells to AIM-100 as shown by CCK8, transwell, and wound healing analyses." (PMID 36647009, 2023). "Most commonly, in lung carcinomas carrying STK11 alterations, the AMPKα1 gene (PRKAA1) is often amplified, while mutations in the PRKAA2 gene occur less frequently." (PMID 32850483, 2020). "Clearly, AMPK inhibitors would be expected to be particularly effective in metabolically compromised tumours that have amplification of the PRKAA1 gene, as is seen in a significant proportion of lung cancers." (PMID 33375416, 2020). "PRKAA1 is a key regulatory kinase in lung cancer-targeted therapies." (PMID 38028209, 2023). "PRKAA1 was also predicted as a new putative kinase in lung cancer." (PMID 28592245, 2017).
lymphoma (8 papers, 2015 to 2024). A malignant (clonal) proliferation of B- lymphocytes or T- lymphocytes which involves the lymph nodes, bone marrow and/or extranodal sites. "Consistent with AMPK-α1 being a tumour suppressor, loss of both alleles of Prkaa1 caused a notable acceleration in the onset of lymphomas, while loss of a single allele caused an intermediate effect." (PMID 33375416, 2020). "Indeed, global knockout in mice of the Prkaa1 gene (encoding AMPK-α1, the only catalytic subunit expressed in lymphocytes) accelerated development of lymphomas induced by B-cell specific over-expression of the Myc oncogene in mice." (PMID 37962491, 2023). "Knockout of Prkaa1 alone did not cause the appearance of any lymphomas, but it accelerated the development of lymphomas induced by loss of the Pten gene." (PMID 33375416, 2020).
colorectal cancer (7 papers, 2014 to 2023). A primary or metastatic malignant neoplasm that affects the colon or rectum. "In determining how dysregulation of the lncRNAs associated with this subpathway is implicated in colorectal cancer pathogenesis, we first noted that the lncRNA DLEU2 (fold-change > 2) competitively regulated AMPK (PRKAA1); the ceRNA dataset supported this association." (PMID 28152521, 2017). "A study by Lee and colleagues showed that STK11, PRKAA1, and TSC1 polymorphisms were associated with disease-free survival after diagnosis with colorectal cancer; they did not see an association with TSC2." (PMID 25541970, 2014).
prostate carcinoma (7 papers, 2013 to 2022). A carcinoma that arises from epithelial cells of the prostate gland. "In DU145 human prostate cancer cells, PRKAA1 activity is required for HIF1A transcriptional activity and expression of HIF1A-targeted genes, but this does not occur through the modulation of HIF1A protein expression, stabilization, or nuclear translocation." (PMID 30405100, 2018). "Metformin and Phenformin (targeting on PRKAA1/PRKAB1 were used for eliminate prostate cancer stem cells." (PMID 29723215, 2018).
type 2 diabetes (6 papers, 2013 to 2026). "In agreement with our study, hepatic SCP2 expression was reduced in diabetic rat, WIPI1 expression were decreased in skeletal muscle from type 2 diabetes, decreased PRKAA1/AMPK phosphorylation was observed in high glucose-induced HK-2 cells." (PMID 35992146, 2022).
glioma (5 papers, 2019 to 2023). A benign or malignant brain and spinal cord tumor that arises from glial cells (astrocytes, oligodendrocytes, ependymal cells). "By processing Pearson correlation analysis to calculate the expression of HTR5A and PRKAA1 in different WHO grading gliomas, we found that the expression levels of HTR5A had a linear correlation with the PRKAA1 in glioma specimens, r=0.48, P <0.05." (PMID 32549758, 2020).
cervical cancer (4 papers, 2007 to 2020). A primary or metastatic malignant neoplasm involving the cervix. "This may hold for hTERT and PRKAA1 as well since it was reported that amplification at 5p in cervical cancer correlated with increased gene and/or protein expression." (PMID 17311676, 2007).
insulinoma (4 papers, 2018 to 2023). "Both transcripts (Prkaa1 and Prkaa2) were enriched in the whole rat islet and particularly abundant in sorted β-cells and non-β-cells compared to insulinoma INS-1E and cells isolated from the hypothalamus." (PMID 32492936, 2020). "Quantitative-RT-PCR analyses of Prkaa1 and Prkaa2 were performed in insulinoma cells and isolated rat islets, as well as FACS-purified rat β- and non β-cells." (PMID 32492936, 2020). "In particular, pancreatic insulinomas (n = 24) showed a higher expression of the autophagic genes BECN1 (p < 0.001), MAP1LC3B (p < 0.001), SQSTM1 (p = 0.008), TFEB (p < 0.001), PRKAA1 (p = 0.038), and PRKAA2 (p = 0.019) compared to NF-pNET (n = 7)." (PMID 36835048, 2023).
leukemia (4 papers, 2019 to 2023). A malignant (clonal) hematologic disorder, involving hematopoietic stem cells and characterized by the presence of primitive or atypical myeloid or lymphoid cells in the bone marrow and the blood. "Thus, to study the role of AMPK in lymphomas and/or leukaemias, it was only necessary to knock out a single gene, i.e. the Prkaa1 gene encoding AMPK-α1." (PMID 31288625, 2019).
lung adenocarcinoma (4 papers, 2018 to 2022). A carcinoma that arises from the lung and is characterized by the presence of malignant glandular epithelial cells. "Amplification of PRKAA1 was particularly common in lung adenocarcinoma, where it occurred in around 10% of cases." (PMID 36383046, 2022). "For example, in 230 cases of lung adenocarcinoma in The Cancer Genome Atlas, STK11 was either deleted or mutated in 43 (19%) and PRKAA1 was amplified in 22 (10%)." (PMID 36383046, 2022). "For example, in 230 cases of lung adenocarcinoma studied by The Cancer Genome Atlas (TCGA) network, the PRKAA1 gene was amplified in 22 (10%), while the STK11 gene (encoding the upstream kinase LKB1) was subject to either deletions, or mutations expected to cause loss-of-function, in 43 (19%)." (PMID 33375416, 2020).
Sepsis (4 papers, 2020 to 2025). Sepsis is defined as life-threatening organ dysfunction caused by a dysregulated host response to infection. "The adenosine monophosphate-activated protein kinase pathway, which is extensively involved in cellular energy homeostasis, was also upregulated and associated with three co-expressed mRNAs (CAB39, PFKFB3, and PRKAA1) in sepsis." (PMID 34907156, 2021). "In addition, metabolism-related genes, including PFKFB3, PRKAA1, PYGL, and GYG1, were also upregulated, which indicated their potential roles in mediating immune responses in sepsis." (PMID 34907156, 2021).
T-cell acute lymphoblastic leukemia (4 papers, 2023 to 2024). Acute lymphoblastic leukemia of T-cell origin. "In fact, miR-19b negatively regulates PRKAA1 and BIM in T-cell acute lymphoblastic leukemia, in addition to PPP2R5E, resulting in an overall PI3K signaling pathway activation." (PMID 37175484, 2023).
Bladder Cancers (3 papers, 2022 to 2024). "The expression of BRM, which is encoded by the SMARCA2 gene, is closely related to the expression of the glycolytic enzyme pyruvate kinase M2 (PKM2) and the AMPKα1-encoding gene (PRKAA1) in bladder cancer cells." (PMID 39609317, 2024). "The Gene Expression Profiling Interactive Analysis (GEPIA) database (source from TCGA) showed that among PRKAA1 (AMPK), SREBP2 and HMGCR, only low expression of SREBP2 in bladder cancer patients showed higher overall survival rates." (PMID 36139556, 2022).
Hypoglycemia (3 papers, 2024 to 2025). A decreased concentration of glucose in the blood. "VMNvl GABA nerve cells showed down-regulated PRKAA1 gene expression during hypoglycemia; this response was reversed by GLUT2 gene knockdown." (PMID 38902332, 2024). "SF-1 stimulates baseline VMNdm Ghrh neuron PRKAA1/AMPKα1 and PRKAA2/AMPKα2 gene expression, yet causes opposite changes in these gene profiles during hypoglycemia." (PMID 39401164, 2024). "Relative PRKAA1 transcription was greater in the VMNvl compared to VMNdm GABA neurons; interestingly, hypoglycemia increased this ratio in the VMNdm, but did not cause evident change in VMNvl neurons." (PMID 38902332, 2024).
osteosarcoma (3 papers, 2012 to 2022). A usually aggressive malignant bone-forming mesenchymal neoplasm, predominantly affecting adolescents and young adults. "LncRNA NBR2 promoted protein kinase AMP-activated catalytic subunit alpha 1 (AMPK) pathway to down-regulate GLUT1 expression and the EMT process, suppressed tumor progression in osteosarcoma cells." (PMID 36072431, 2022).
B cell lymphoma (2 papers, 2019). "Consistent with the idea that AMPK-α1 is a tumour suppressor, loss of both alleles of Prkaa1 in this model markedly accelerated development of B-cell lymphomas, whereas loss of a single allele had an intermediate effect." (PMID 31288625, 2019). "A drawback with this B-cell lymphoma model was that Prkaa1 was knocked out globally, so it was not possible to conclude that the effect was due to a cell-autonomous loss of AMPK-α1 in the B-cell progenitors themselves, rather than an indirect effect of loss of AMPK-α1 in some other cell type." (PMID 31288625, 2019).
cardia cancer (2 papers, 2016). A malignant neoplasm involving the cardia of stomach. "Similarly, PLCE1 rs2274223 and PTGER4 and PRKAA1 rs13361707 were used to predict the risk of cardia cancer in populations with a hereditary background, who faced a greater than 3-fold higher risk (P < 0.05*)." (PMID 27127881, 2016). "Also those with a hereditary background including the risk alleles PLCE1 rs2274223 and PTGER4/PRKAA1 rs13361707 were 3 times more susceptible to cardia cancer than those without." (PMID 27127881, 2016).
coronary artery disease (2 papers, 2018 to 2025). "In EAT from patients with coronary artery disease, PGC-1α gene expression is downregulated, SIRT1 expression correlates positively with RELA, and miR-1247-5p expression is reduced, negatively correlating with BMI and PRKAA1 (which encodes the catalytic α-1 subunit of AMPK)." (PMID 41425991, 2025).
schizophrenia (2 papers, 2024 to 2026). A major psychotic disorder characterized by abnormalities in the perception or expression of reality.
Alzheimer disease (1 paper, 2022). A progressive, neurodegenerative disease characterized by loss of function and death of nerve cells in several areas of the brain leading to loss of cognitive function such as memory and language. "These include APOE, PRKAA1, and MAP3K1, which were previously reported to be associated with Alzheimer’s disease (AD)." (PMID 35580864, 2022).
astrocytic tumor (1 paper, 2024). A glial tumor of the brain or spinal cord showing astrocytic differentiation. "Our analysis of the mRNA expression patterns of PRKAA1 and PRKAA2, along with their encoded proteins, revealed that their expression increases with the grade of the astrocytic tumor." (PMID 39001398, 2024).
autism (1 paper, 2021). Persistent deficits in social interaction and communication and interaction as well as a markedly restricted repertoire of activity and interest as well as repetitive patterns of behavior. "PRKAA1 has also been reported in several studies related to autism and/or ASD including linkage studies, NGS de novo mutation studies, and genome-wide association studies." (PMID 33716802, 2021).
carcinoma of the stomach (1 paper, 2018). "PRKAA1 encodes α-subunit of 5-AMP-activated protein kinase (AMPK), which has been implicated in the pathogenesis of carcinoma of the stomach." (PMID 30253744, 2018).